APAF1 (apoptotic peptidase activating factor 1)
Diseases named in the same sentence as APAF1 in open-access papers (continued):
Sharing a sentence is not in itself a finding about the gene and the disease.
metastatic melanoma (5 papers, 2004 to 2021). A melanoma that has spread from its primary site to another anatomic site. "E.g. in metastatic melanoma resistance is reported to be linked to defective apoptosis due to inhibition of expression of a gene encoding Apaf-1, the apoptotic protease activating factor-1." (PMID 29069749, 2017). "Specifically, loss of heterozygosity (LOH) of the Apaf-1 gene was found in 40% of metastatic melanoma." (PMID 15305193, 2004). "It is also known that Apaf1 is inactivated in metastatic melanomas." (PMID 27342975, 2016). "In total, we analysed the expression of six pro-apoptotic (Bax, Bak, Smac, Procaspase-9, Apaf-1, Procaspase-3) and three antiapoptotic proteins (Bcl-2, Bcl-xL, XIAP) in metastatic melanoma samples spotted on TMAs." (PMID 32054850, 2020). "In this study, we therefore assessed the expression of nine apoptosis regulators (Bax, Bak, Bcl-2, Bcl-xL, Smac, Procaspase-9, Apaf-1, Procaspase-3 and XIAP) in metastatic melanoma tissues by immunohistochemistry (IHC), using antibodies that passed rigorous validation." (PMID 32054850, 2020). "Specifically, LOH of Apaf-1 alleles was detected in 42% of the metastatic melanoma specimens and more than 50% of cell lines that derived from metastatic melanoma showed negative Apaf-1 expression." (PMID 15305193, 2004).
pancreatic cancer (5 papers, 2020 to 2024). "COL11A1/Akt disturbed the BCL-2/BAX balance, inhibiting cytochrome c (Cyt-C) release and binding of Apaf-1/procaspase-9/Cyt-C, which suppressed the apoptotic program and induced GEM resistance in pancreatic cancer cells." (PMID 33531986, 2021).
cardiac ischemia (4 papers, 2016 to 2024). "Excessive Apaf-1 activity induced by myocardial ischemia causes cell injury." (PMID 27443636, 2016). "We conclude that APPL1 inhibits myocardial ischemia/hypoxia-reperfusion injury via inactivation of APAF-1/Caspase9 signaling pathway." (PMID 34304702, 2021). "In conclusion, ZYZ-488 as a novel small molecule competitive inhibitor of Apaf-1, with the great potential for treating cardiac ischemia." (PMID 27443636, 2016). "Taken together, APPL1 knockdown suppressed the viability of myocardial ischemia cells and aggravated hypoxia/reperfusion-induced LDH hypersecretion, inflammation and apoptosis, which was, to our interest, abrogated by APAF1 inhibitor." (PMID 34304702, 2021). "No drug targeted to Apaf-1 for treating myocardial ischemia has been reported to the best of our knowledge." (PMID 27443636, 2016). "For example, inhibition of apoptosis protease activating factor-1 (Apaf-1), a key regulatory enzyme of the apoptosis pathway, by a novel inhibitor (ZYZ-488) was found to have a protective effect on cardiomyocytes in cardiac ischemia." (PMID 39062012, 2024).
Cerebral ischemia (4 papers, 2013 to 2026). Restriction of arterial blood supply to the brain associated with insufficient oxygenation to support the metabolic requirements of the tissue. "They found that promoting blood circulation and removing blood stasis reduced APAF‐1, caspase‐9, and caspase‐3 in cerebral ischemia model rats, and inhibited the apoptosis of the hippocampal neurons by modulating the APAF‐1‐mediated caspase pathway." (PMID 40566933, 2025). "Indeed, preventing the interaction of Apaf-1 with Cytc has been shown to be a potent neuroprotective strategy following brain ischemia." (PMID 24223835, 2013).
cutaneous melanoma (4 papers, 2004 to 2021). A primary melanoma arising from atypical melanocytes in the skin. "In human cutaneous melanoma, evasion of apoptosis occurs through upregulation of BCL2 and/or loss of APAF-1." (PMID 34822659, 2021). "Many of them were previously appreciated in the genome of skin melanomas (e.g., MITF, NOTCH2, PD-L1 and JAK2 amplifications, or CDKN2A deletions); however, the CNAs in genomic locations harboring PAX5, ETS1, BCL7, RAD51, APAF1, FOXO3 and CTNNA1 are novel." (PMID 33779796, 2021).
glioblastoma (4 papers, 2016 to 2022). The most malignant astrocytic tumor (WHO grade IV). "Our previous study on apoptotic gene expression revealed a slight decrease in the expression of APAF1 in glioblastoma patient samples." (PMID 36142793, 2022). "For example, U87-MG glioblastoma cells and Apaf-1-null MEFs could be induced to detach from culture dishes without any evidence of caspase-3 activation, and thus fail to meet the criteria for anoikis." (PMID 29494533, 2018).
Hyperglycemia (4 papers, 2015 to 2021). An increased concentration of glucose in the blood. "In case of hyperglycemia, the mitochondrial membrane's potential is disturbed, and it secretes cytochrome c which then causes activation of procaspase-9 along with apoptotic protease activating factor-1 (Apaf-1) resulting in the caspase-3 activation in neurons." (PMID 34093722, 2021). "In addition, hyperglycemia stimulated apoptotic bax signaling, mitochondrial pathways of cytochrome C/Apaf-1 apoptosomes and proteolytic caspase activation in mouse eyes." (PMID 33076507, 2020). "This study evaluated the neuroprotective effects of piperine and expression of five candidate genes (BACE1, PSEN1, APAF1, CASPASE3, and CATALASE) in rat’s cerebral cortex induced hyperglycemia with STZ rat model." (PMID 33737876, 2020).
ischemic stroke (4 papers, 2020 to 2025). A stroke disorder caused by obstruction of blood flow to the brain, due to thrombotic (local blood clot formation) or embolic (due to a blood clot or other material traveling from another site) event. "Mitochondria damaged by ischemic stroke release cytochrome c, which binds to the apoptotic protease activating factor 1 (Apaf-1) and procaspase-9, forming apoptotic bodies and initiating a series of apoptotic events." (PMID 40881626, 2025). "Interestingly, in acute MI and ischemic stroke, the expression of APAF1 and IRAK3 was negatively correlated with the abundance of NK cells, while the expression of ATM, CAPN1, IL1B, IL1R1, PRKACA, PRKACB and TNFRSF1A was positively correlated with the abundance of NK cells in MI." (PMID 38526027, 2024). "Interestingly, APAF1 and IRAK3 expression correlated negatively with NK cell abundance in both acute myocardial infarction and ischemic stroke, whereas ATM, CAPN1, IL1B, IL1R1, PRKACA, PRKACB, and TNFRSF1A correlated negatively with NK cell abundance in acute myocardial infarction." (PMID 35432334, 2022).
Stroke (4 papers, 2014 to 2022). Sudden impairment of blood flow to a part of the brain due to occlusion or rupture of an artery to the brain. "For example, miRNA 23a, miR-23b, miR-24, and miR-27a are known to target APAF1 and pro-apoptotic BCL family proteins and thereby prevent neuronal apoptosis, and downregulation of these miRNAs during acute EAE, TBI, spinal cord injury, and stroke is thought to contribute to neuron and neurite loss." (PMID 36261842, 2022). "In addition, Apaf-1 (apoptotic associated factor 1), FADD (Fas (TNFRSF6)-associated via death domain) and Bcl-2, up regulated in female cardioembolic stroke, have all been associated with female cell death following stroke." (PMID 25036109, 2014).
viral infection (4 papers, 2015 to 2025). "This phenomenon is consistent with previous studies showing that the intrinsic apoptosis deficiency caused by knocking out Apaf-1 augments the IFN response in basal or viral infection conditions via the mtDNA-dependent cGAS-STING activation." (PMID 39833169, 2025). "Various death stimuli or viral infections can lead to an increase in the permeability of the outer mitochondrial membrane, causing the release of cytochrome C and binding to apaf-1, thereby enabling the assembly of apaf-1 apoptotic bodies and activation of caspase-9." (PMID 33692782, 2021).
cervical carcinoma (3 papers, 2011 to 2018). A carcinoma arising from either the exocervical squamous epithelium or the endocervical glandular epithelium. "Activation of caspase-9 is mediated by the Apaf-1 apoptosome and caspase-9 induces apoptosis through caspase-3 activation in human cervical cancer cells." (PMID 30627573, 2018). "Remarkably, the concentration of pc-9 and Apaf-1 in HeLa cervical cancer cells is estimated to be ~30 nM and ~340 nM, respectively (Würstle and Rehm, 2014)." (PMID 27697150, 2016).
Huntington disease (3 papers, 2019 to 2023). Huntington disease (HD) is a rare neurodegenerative disorder of the central nervous system characterized by unwanted choreatic movements, behavioral and psychiatric disturbances and dementia. "In contrast, increased levels of Apaf-1 protein are observed in the brain in Huntington’s disease." (PMID 31329620, 2019). "Increased endogenous levels of Apaf-1 protein have been observed in human brain tumors, a consequence of E2F1 transcriptional activity, and in Huntington’s disease (HD) and its mouse and fly models." (PMID 31329620, 2019).
acute myocardial infarction (2 papers, 2017 to 2022). Necrosis of the myocardium, as a result of interruption of the blood supply to the area. "In conclusion, our findings present the first piece of evidence indicating the interaction between Apaf-1 and procaspase-9 as a novel therapeutic target in myocardial infarction and suggesting ZYZ-488 as a promising therapeutic option for myocardial infarction disease." (PMID 29279737, 2017). "As the first molecule reported to reduce cardiomyocyte apoptosis by targeting Apaf-1, the potential of ZYZ-488 for treating myocardial infarction in vivo is unknown." (PMID 29279737, 2017).
Alzheimer disease (2 papers, 2014 to 2015). A progressive, neurodegenerative disease characterized by loss of function and death of nerve cells in several areas of the brain leading to loss of cognitive function such as memory and language. "Among those genes, Apaf1, Bace2, and Plcb4 were enriched in the “Alzheimer's disease-reference pathway” and downregulated after ME intervention." (PMID 25580148, 2014). "Furthermore, the Apaf1 inhibitor has been used to confirm the effect of caspase-3 inhibition on GluR1 synaptic distribution in a mouse model of Alzheimer’s disease." (PMID 26361785, 2015).
astrocytoma (2 papers, 2004 to 2011). "Seventeen genes (ABL, APC, APAF1, BRCA1, CSPG2, DAPK1, hMLH1, LKB1, PTEN, p14ARF, p15INK4b, p27KIP1, p57KIP2, RASSF1C, RB1, SURVIVIN, and VHL) displayed a uniformly unmethylated pattern in all the astrocytoma and non-astrocytoma tissues examined." (PMID 15367334, 2004).
chronic myeloid leukemia (2 papers, 2019 to 2021).
Diabetes (2 papers, 2020 to 2025). "In STZ treated group (Diabetes control), the expression of BACE1, PSEN1, APAF1, CASPASE3, and CATALASE genes were upregulated in the cerebral cortex of the rat brain as compared to the untreated group (Vehicle control)." (PMID 33737876, 2020).
diffuse large B-cell lymphoma (2 papers, 2011 to 2016). "Here we provide evidence that the apoptosome adaptor protein, Apaf-1, is mislocalized in primary cells derived from patients with diffuse large B cell lymphomas (DLBCL)." (PMID 27863378, 2016).
epidermoid carcinoma (2 papers, 2014 to 2020). "APAF1, a critical component of the apoptosome to promote endogenous apoptotic process, was verified to be a functional target of miR-186 in tissues and cells of squamous cell carcinoma (cSCC)." (PMID 32195180, 2020). "In endometrial cancer tissues and squamous cell carcinoma tissues, miR-186 served as an oncomir by suppressing targets P2RX7, FOXO1, APAF1, and RETREG1." (PMID 32195180, 2020).
immune deficiency (2 papers, 2019 to 2025). "The present study investigated the influence of functional SNPs associated with the APAF1 gene via in silico methods because APAF1 is related to many diseases such as cancer, neurodegenerative disorders, heart disease, autoimmunity, and immunodeficiencies." (PMID 31892812, 2019).
ischemia (2 papers, 2016 to 2025). A hypoperfusion of the BLOOD through an organ or tissue caused by a PATHOLOGIC CONSTRICTION or obstruction of its BLOOD VESSELS, or an absence of BLOOD CIRCULATION. "Apaf-1 immunohistochemical stained sections of the control group revealed weak reaction of spermatogenic cells, whereas there were multiple germinal cells with dark brown apoptotic nuclei in ischemia only group and I/R group." (PMID 28101298, 2016). "When stimulated by ischemia, CYT-C translocates from the mitochondria to the cytoplasm, where it binds to Apaf-1, recruits caspase-9 to form apoptotic bodies, activates caspase-3, and promotes apoptosis." (PMID 40703757, 2025).
male infertility (2 papers, 2012 to 2025). The inability of the male to effect fertilization of an ovum after a specified period of unprotected intercourse.
myelodysplastic syndrome (2 papers, 2015 to 2017). A clonal hematopoietic disorder characterized by dysplasia and ineffective hematopoiesis in one or more of the hematopoietic cell lines. "High Apaf-1 expression elevates erythroid apoptosis in iron overload myelodysplastic syndrome." (PMID 26448723, 2015). "In this study, we investigated the relation of APAF1 methylation status with its expression and clinicopathological factors in myelodysplastic syndrome (MDS) patients." (PMID 28875006, 2017).
Parkinson disease (2 papers, 2015 to 2023). A progressive degenerative disorder of the central nervous system characterized by loss of dopamine producing neurons in the substantia nigra and the presence of Lewy bodies in the substantia nigra and locus coeruleus. "The expression levels of APAF1 were correlated with scores for parkinsonism, as measured by the UPDRS and PDQ-39, while the expression levels of CSF1R were negatively correlated with scores for cognitive function, as measured by the MMSE and MoCA." (PMID 37108258, 2023). "This makes the Ubc13 and APAF1 pair an attractive multitarget for development of therapeutics with polypharmacological mechanisms of action in Parkinson's disease." (PMID 25991664, 2015). "Thus, both Ubc13 and APAF1 are potential therapeutic targets in Parkinson's disease but with different mechanism of action." (PMID 25991664, 2015). "Recently APAF1 dominant negative inhibition was tested for its anti-apoptotic effect on degenerating nigrostriatal neurons in a 1-methyl-4-phenyl-1,2,3,6-tetrahydropyridine (MPTP) model of Parkinson's disease and was shown to inhibit MPTP toxicity." (PMID 25991664, 2015).
pituitary adenomas (2 papers, 2019). "A bidirectional-inverted relationship between APAF-1 and cathepsin B expressions may result in changes in pituitary adenoma behavior." (PMID 31649621, 2019). "In addition, studies also showed that low levels of APAF-1 were inversely related to invasiveness, and cathepsin B expression was positively related to invasiveness in pituitary adenomas." (PMID 31920968, 2019). "Low expression of APAF-1 was detected in most invasive pituitary adenomas, and was negatively correlated with the aggressive behavior of invasive pituitary adenoma, which suggested that shifting the balance of apoptosis mediators in cells could lead to changes of pituitary tumor behaviors." (PMID 31649621, 2019).
prostate carcinoma (2 papers, 2018 to 2022). A carcinoma that arises from epithelial cells of the prostate gland. "Downregulation of inhibitors of apoptosis (IAP) family proteins and apoptotic protease activating factor 1 (Apaf-1) in SFN treatment on prostate cancer cell lines stimulated the cell death." (PMID 30445746, 2018).
psoriasis (2 papers, 2018 to 2020). An autoimmune condition characterized by red, well-delineated plaques with silvery scales that are usually on the extensor surfaces and scalp. "For instance, MEG3/miR-21 axis contribute in the pathophysiology of psoriasis through modulation of caspase-8, cleaved caspase-8, cytc, and apaf-1." (PMID 32695942, 2020).
rectal cancer (2 papers, 2008). A primary or metastatic malignant neoplasm that affects the rectum.
abortion (1 paper, 2023). the ending of pregnancy by removing a fetus or embryo before it can survive outside the uterus. "As a result, we identified a nonsense mutation in apoptotic protease activating factor 1 (APAF1) within HH1 that was associated with a decrease in conception rate and an increase in abortion in Holstein dairy cattle." (PMID 37671278, 2023).
acute respiratory distress syndrome (1 paper, 2024). Progressive and life-threatening pulmonary distress in the absence of an underlying pulmonary condition, usually following major trauma or surgery. "Similarly, HSP70 overexpression inhibited caspase 3, 8, 9, APAF-1 and Bcl2 activation, preventing Acute Respiratory Distress Syndrome (ARDS) induced by cecal ligation and puncture in rats." (PMID 38339194, 2024).
African trypanosomiasis (1 paper, 2024). "APAF-1 is linked to antifolate resistance and interleukin-1 receptor binding, while TNF-α is implicated in choline binding and infections like malaria and African trypanosomiasis." (PMID 39063550, 2024).
age-related hearing loss (1 paper, 2018). "Comparable changes of intrinsic pro- and anti-apoptotic signaling, including regulation of BCL2 family members and APAF1, were also shown during age-related hearing loss (ARHL)." (PMID 29867323, 2018).
aging (1 paper, 2020). A developmental process that is a deterioration and loss of function over time. "Herein, mapping the interplay between these functions is essential for a complete understanding of the roles of Apaf-1 in health and aging diseases." (PMID 32641103, 2020).